ARG2 (arginase 2)
Description:
May play a role in the regulation of extra-urea cycle arginine metabolism and also in down-regulation of nitric oxide synthesis. Extrahepatic arginase functions to regulate L-arginine bioavailability to nitric oxid synthase (NOS). Arginine metabolism is a critical regulator of innate and adaptive immune responses. Seems to be involved in negative regulation of the survival capacity of activated CD4(+) and CD8(+) T cells. May suppress inflammation-related signaling in asthmatic airway epithelium. May contribute to the immune evasion of H.pylori by restricting M1 macrophage activation and polyamine metabolism (By similarity). In fetal dendritic cells may play a role in promoting immune suppression and T cell TNF production during gestation. Regulates RPS6KB1 signaling, which promotes endothelial cell senescence and inflammation and implicates NOS3/eNOS dysfunction. Can inhibit endothelial autophagy independently of its enzymatic activity implicating mTORC2 signaling. Involved in vascular smooth muscle cell senescence and apoptosis independently of its enzymatic activity. Since NOS is found in the penile corpus cavernosum smooth muscle, the clitoral corpus cavernosum and the vagina, arginase-2 plays a role in both male and female sexual arousal.
Tractability: Small molecule: a structure with a bound ligand is known; a high-quality ligand is known; it has a high-quality binding pocket. PROTAC: its protein half-life has been measured; a small molecule that binds it is known.
Target class: Enzyme; Hydrolase
Gene: Protein-coding gene on chromosome 14 (67,619,920 to 67,651,708, forward strand). Ensembl gene ENSG00000081181.
Subcellular location: Mitochondrion
Subcellular location (Human Protein Atlas): Mitochondria
Pathways (Reactome):
Metabolism: Urea cycle
Metabolism of proteins: Mitochondrial protein degradation
Gene Ontology:
Molecular function: arginase activity; protein binding; manganese ion binding; hydrolase activity, acting on carbon-nitrogen (but not peptide) bonds, in linear amidines; metal ion binding
Biological process: negative regulation of tumor necrosis factor production; positive regulation of cellular senescence; nitric oxide biosynthetic process; urea cycle; arginine metabolic process; negative regulation of activated CD8-positive, alpha-beta T cell apoptotic process; negative regulation of CD4-positive, alpha-beta T cell proliferation; negative regulation of chemokine (C-C motif) ligand 4 production; negative regulation of chemokine (C-C motif) ligand 5 production; negative regulation of defense response to bacterium; negative regulation of interleukin-13 production; negative regulation of interleukin-17 production; negative regulation of macrophage inflammatory protein 1 alpha production; negative regulation of multicellular organismal process; negative regulation of type 2 immune response; regulation of interleukin-1 beta production; regulation of reactive oxygen species biosynthetic process; ureteric bud development
Cellular component: mitochondrion; cytoplasm; mitochondrial matrix
Genetic constraint (gnomAD): Loss-of-function variants: 19 observed, 35.75 expected, observed/expected ratio (o/e) 0.53, 90% interval 0.37 to 0.78. The upper end of that interval is the gene's LOEUF score, 0.78, which puts it in group 3 of 6, group 1 being the genes least tolerant of losing a copy. Missense variants: 354 observed, 426.83 expected, observed/expected ratio (o/e) 0.83, 90% interval 0.76 to 0.91. Synonymous variants: 144 observed, 159.17 expected, observed/expected ratio (o/e) 0.9, 90% interval 0.79 to 1.04.
Homologues: Orthologues: chimpanzee ARG2 (100% identical), macaque ARG2 (99% identical), dog ARG2 (93% identical), pig ARG2 (93% identical), guinea pig ARG2 (88% identical), mouse Arg2 (85% identical), rat Arg2 (84% identical), rabbit ARG2 (79% identical), tropical clawed frog arg2 (73% identical), zebrafish arg2 (61% identical), Drosophila melanogaster arg (39% identical). Paralogues in human: ARG1 (54% identical), AGMAT (25% identical).
Diseases named in the same sentence as ARG2 in open-access papers:
ARG2 is named in the same sentence as 155 diseases in open-access papers, as found by Europe PMC text mining. Sharing a sentence is not in itself a finding about the gene and the disease. The quoted sentences say what the papers report.
endothelial dysfunction (24 papers, 2012 to 2025). In vascular diseases, endothelial dysfunction is a systemic pathological state of the endothelium (the inner lining of blood vessels) and can be broadly defined as an imbalance between vasodilating and vasoconstricting substances produced by (or acting on) the endothelium. "It is understandable that endothelial dysfunction caused by enhanced ARG2 levels would reduce coronary perfusion and in turn decrease cardiac contractile function as reported in the literature." (PMID 41187268, 2025). "Arginase is an enzyme that metabolizes L-arginine into L-ornithine and urea, and is associated with endothelial dysfunction and aging, which have two isoforms, namely arginase 1 (Arg1) and arginase 2 (Arg2), with Arg2 being the predominant isoform induced in human ECs’ mitochondria." (PMID 40636522, 2025). "SIRT1 activation reverses endothelial dysfunction in microvessels isolated from subcutaneous adipose tissue of old patients, which is associated with lower p66Shc and Arginase II (Arg2) levels, and increased expression of mitochondrial enzymes with antioxidant properties, such as SIRT3 and SOD2." (PMID 37274126, 2023). "Both ARG1 and ARG2 are found in endothelium and have been implicated in endothelial dysfunction." (PMID 29890043, 2018). "However, Epimedium fried with suet oil could significantly reduce the ARG2 expression levels, indicating that it might play its role by reducing ARG2 expression levels and alleviating the endothelial dysfunction caused by its overexpression." (PMID 36762111, 2023). "One animal study showed that Arg2 is the key isoform responsible for the total arginase activity in the aorta of aging mice, leading to eNOS uncoupling and endothelial dysfunction." (PMID 39952693, 2025). "Previous studies demonstrated that upregulation of arginase-2, COX-2, and NADPH oxidase pathways was involved in endothelial dysfunction associated with AIA." (PMID 35488311, 2022). "Studies have shown that over-activation of ARG2 in aorta and decrease of eNOS can lead to endothelial dysfunction." (PMID 32892299, 2020). "Using a gene deletion model, we investigated involvement of arginase isoforms arginase 1 and 2 (ARG1 and ARG2) in hypertension and endothelial dysfunction in a mineralocorticoid-salt mouse model." (PMID 23908657, 2013). "Acacetin is dependent on estrogen-like action to reduce the levels of inflammatory factors, inhibit ERK pathway, down-regulate ARG2 and increase NO to relax the blood vessels, so as to alleviate endothelial dysfunction and improve the aortic fibrosis of SHR rats with insulin-resistant." (PMID 32892299, 2020).
atherosclerosis (22 papers, 2012 to 2025). A disease characterized by the build-up of fatty material and calcium deposition in the arterial wall resulting in partial or complete occlusion of the arterial lumen. "Our previous study demonstrated that ARG2 plays a role in macrophage infiltration in different organ/tissues in high-fat diet and high-cholesterol diet-induced atherosclerosis and obesity mouse models." (PMID 41187268, 2025). "Arginase 2 (Arg2) is a critical regulator in atherosclerosis progression that controls vascular inflammation." (PMID 39281836, 2024). "Reduces LDL-C, MDA and IL-6 levels; increases NO and eNOS levels; decreases plaque area in the aortic lumen of mice; improves lipid deposition; down-regulates PARP1, ARG2 and iNOS expression in mouse aortic tissue; and slows down atherosclerosis." (PMID 35566359, 2022). "For instance, some proteins related to atherosclerosis were down-regulated in SF, such as ARG2, CD14, CD44, engulfment, and cell motility protein 1 (ELMO1), neutrophil gelatinase-associated lipocalin (LCN2), MPO, S100A8, or S100A9." (PMID 34572333, 2021). "ARG2 is associated with nitric oxide synthase 3 (NOS3)/eNOS dysfunction in the pathogenesis of vascular aging and atherosclerosis." (PMID 34943028, 2021). "ARG2 promotes proinflammatory responses in macrophages and contributes to evidence of atherosclerosis and obesity-related insulin resistance." (PMID 32462040, 2020). "In animal models with atherosclerosis, ARG2-dependent increases in ROS can lead to endothelial cell dysfunction." (PMID 33117340, 2020). "It is noteworthy that ARG2-positive macrophages prevailed in chronic inflammatory lesions of atherosclerosis patients." (PMID 31969876, 2019). "In support of this conclusion, chronic inflammatory diseases such as atherosclerosis and type 2 diabetes, inflammaging in lung, kidney, and pancreas of aged animals or acute organ injury such as acute ischemic/reperfusion or cisplatin-induced renal injury are reduced in the Arg2-/- mice." (PMID 41187268, 2025). "In addition, in a late stage of human carotid plaques, ARG2 activation in ECs and macrophages can trigger ROS formation, which may further enhance atherosclerosis progression." (PMID 36209203, 2022). "In atherosclerosis, overexpression of HDAC2 in endothelial cells under proatherogenic conditions and oxidative injury suppresses the expression of Arginase2 (ARG2), which further reduces the expression of endothelial nitric oxide synthase (eNOS)." (PMID 36909892, 2023). "ARG2 impairs endothelial autophagy through the modulation of the mTOR and PRKAA/AMPK signaling in advanced atherosclerosis." (PMID 34943028, 2021). "In contrast to ARG2, ARG1 upregulation has been reported to ameliorate atherosclerosis, manifested as dampening atherosclerotic plaque inflammation, increasing Th2 cytokine levels, and facilitating VSMC proliferation, ultimately leading to the elevated atherosclerotic plaque stability." (PMID 36209203, 2022). "Afterward, increased activity of ARG2, irrespective of plasma lipid levels, was sufficient to induce inflammatory changes and atherosclerosis formation." (PMID 33117340, 2020). "Our data identified a critical protective role for monocytic Grx1 in atherosclerosis and obesity and revealed a negative feedback mechanism between Grx1 activity and the expression of NADPH oxidases (NOX), nitric oxide synthases (NOS), and arginase 2 (ARG2)." (PMID 35145079, 2022).
Obesity (20 papers, 2014 to 2025). Accumulation of substantial excess body fat. "It is also notable that the mitochondrial isoform of arginase (Arg2) plays a critical role in obesity-associated pancreatic cancer." (PMID 30697165, 2018). "Altogether, these data suggest an increased dependence of obesity-associated tumors on ARG2 for nitrogen disposal." (PMID 28808255, 2017). "Consistent with a strong dependence of obesity-associated PDA on ARG2, this tumor had re-expressed ARG2 in vivo (lane 11)." (PMID 28808255, 2017). "We find that the mitochondrial form of arginase (ARG2), which hydrolyzes arginine into ornithine and urea, is induced upon obesity, and silencing or loss of ARG2 markedly suppresses PDA." (PMID 28808255, 2017). "Here the authors show that obesity induces the expression of the mitochondrial form of arginase ARG2 in PDA and that ARG2 silencing or loss results in ammonia accumulation and suppression of obesity-driven PDA tumor growth." (PMID 28808255, 2017). "Upregulation of ARG2 in the obese group may be associated with cell proliferation and chronic inflammation caused by obesity." (PMID 32462040, 2020). "Because ARG2 was induced in obesity-associated tumors, we asked whether its role in PDA growth was relevant in an in vivo, rather than in vitro setting." (PMID 28808255, 2017). "In a model of obesity-driven pancreatic cancer, Arg2 is upregulated in epithelial cells, and its knockdown reduces tumor growth in a cell autonomous manner, independently from immune responses." (PMID 36727849, 2023). "Our previous study discloses that obesity-induced ARG2 upregulation enhances mitochondrial ROS production, subsequently accelerating the development of obesity-associated IR." (PMID 36338341, 2022). "ARG2, also has been found to be upregulated in obesity mice, which contributes to IR via the promotion of hydrogen peroxide production and proinflammatory responses." (PMID 36338341, 2022). "Accordingly, ARG2 knockdown inhibits tumour growth, severely impairing tumour initiation in obesity conditions." (PMID 34588983, 2021). "As an important enzyme at the final step of the urea cycle, the obesity-induced upregulated ARG2 enhances nitrogen flux into the urea cycle." (PMID 33987528, 2021). "Compared with the obesity group, the expression of ARG2, COX5B, and ZNT1 in the ZnSO4-treated group was significantly decreased, while the expression of LYAR and TM165 was significantly increased." (PMID 32462040, 2020). "Our lab showed the critical role of arginase 2 (A2), the mitochondrial isoform of this ureahydrolase, in obesity-induced metabolic dysfunction and inflammation." (PMID 31979105, 2020). "We conclude that hepatocyte Arg2 is a critical effector of the hepatic glucose fasting response and define a therapeutic target to mitigate the complications of obesity and non-alcoholic fatty liver disease." (PMID 30962478, 2019). "We therefore sought to investigate the role of ARG2 in an obesity-independent model of PDA with enhanced tumor growth." (PMID 28808255, 2017). "In the current study, although BMI does not significantly impact the immune microenvironment of PTC, HMGB1 is downregulated in underweight individuals and individuals with obesity, and ARG2 is upregulated in the obesity condition, suggesting their involvement in cancer-related processes." (PMID 40943211, 2025). "Interestingly, ARG2, the extrahepatic mitochondrial enzyme that catabolizes arginine into ornithine and urea, is induced upon obesity." (PMID 40943211, 2025). "Our group also found that increase of ARG2 promoted eNOS uncoupling and vascular dysfunction via the activation of p38 MAPK in HFD-induced obesity mice, which could be prevented by ARG2 gene knockout." (PMID 36338341, 2022). "Opposing findings employing Arg2-deficient mice have shown that Arg2-deficiency results in development of spontaneous hepatic steatosis and increased liver injury or promotes decreased NAFLD severity in obesity." (PMID 31921154, 2019).
Obesity (continued). "Consistent with an increase in nitrogen levels in obesity-associated PDA, we found a significant accumulation of 15N-ammonia in tumors of the obese, the levels of which tended to further increase upon ARG2 knockdown (P ≤ 0.05, one-way ANOVA followed by Tukey test)." (PMID 28808255, 2017). "The specific dependency of PDA on ARG2 rather than the principal hepatic enzyme ARG1 opens a therapeutic window for obesity-associated pancreatic cancer." (PMID 28808255, 2017). "A recent study showed that the induction of ARG2 would promote the growth of pancreatic ductal adenocarcinoma, by directing metabolic nitrogen flow into the urea cycle; this condition could be increased by obesity and metabolic syndrome, characterized by an overabundance of nutrients." (PMID 40943211, 2025). "It has been shown that arginine catabolism by the enzyme arginase 2 (ARG2) supports PDAC tumour growth, specially in an obesity context." (PMID 34588983, 2021). "Importantly, because ARG1 and not ARG2 is the main hepatic ureagenic enzyme in mammals, specific targeting of ARG2 may provide a therapeutic opportunity for the treatment of pancreatic cancer patients, particularly those suffering from obesity and the metabolic syndrome." (PMID 28808255, 2017). "In particular, we find that arginase 2 (ARG2), the extrahepatic mitochondrial enzyme that catabolizes arginine into ornithine and urea is induced upon obesity." (PMID 28808255, 2017). "Obesity or AKT activation might further exaggerate this process, generating excess levels of nitrogen and creating a dependency on ARG2." (PMID 40943211, 2025). "Consequently, ARG2 provides an attractive therapeutic target in PDA patients, particularly those suffering from obesity or those with AKT-driven PDA tumors resulting from activating oncogenic mutations, independent of obesity." (PMID 28808255, 2017). "We therefore propose that conditions that enhance PDA growth in vivo, such as obesity or AKT activation, might further exaggerate this process, generating excess levels of nitrogen and creating a dependency on ARG2." (PMID 28808255, 2017). "The role of ARG2 has been investigated in cardiovascular disease, fibroblasts senescence, melanosomes senescence, nonalcoholic fatty liver disease (NAFLD) associates with obesity and type 2 diabetes, pancreatic cancer, and non-small-cell lung cancer." (PMID 40943211, 2025). "Consistently, ARG2 expression was markedly increased in the tumors harboring constitutively active AKT, independent of obesity (P ≤ 0.001, one-way ANOVA followed by Tukey test)." (PMID 28808255, 2017).